CCND1 (cyclin D1)
Diseases named in the same sentence as CCND1 in open-access papers (continued):
Sharing a sentence is not in itself a finding about the gene and the disease.
gastric cancer (continued). "In order to further validate whether NCAPD3 directly targets CCND1, ESR1, and MYC to regulate gastric cancer cell proliferation, Co-IP experiments were conducted to examine if NCAPD3 directly interacts with CCND1, ESR1, and MYC." (PMID 38711992, 2024). "Moreover, cynaroside, derived from Alpinia katsumadai, suppresses cyclin D1 expression and regulates the MET/AKT/mTOR signaling pathway, inhibiting both proliferation and migration of gastric cancer cells." (PMID 39906672, 2024). "The carbohydrate response element binding protein (CHREBP) is downregulated in gastric cancer and inhibits Cyclin D1 levels in gastric cancer cells in order to suppress growth via negative modulation of the Cyclin D1-Rb-E2F1 signaling mechanism." (PMID 36769170, 2023). "In gastric cancer, researchers found that METTL16 is highly expressed in cancer tissues, and METTL16-mediated m6A methylation promotes GC cell proliferation by enhancing cyclin D1 expression." (PMID 37182151, 2023). "Furthermore, another gastric cancer promoter protein named a DEAD cassette helicase 21 (DDX21), which is an ATP-dependent RNA helicase, is involved in upregulating the expression of Cyclin D1 and CDK2." (PMID 36769170, 2023). "Moreover, analyses of Western blot and RT-qPCR suggested that β-catenin overexpression was able to rescue KLF13-mediated down-regulation of CCND1 and MYC expressions in both gastric cancer cell lines." (PMID 36336731, 2022). "Based on these results, we speculated that β-catenin-dependent CCND1 and MYC transcriptions appeared to be involved in KLF13-induced suppression of gastric cancer proliferation." (PMID 36336731, 2022). "Upon the analysis of the TCGA dataset of 415 human gastric cancer tissue samples and 34 normal stomach samples, a dramatic increase in the mRNA levels of β-catenin (CTNNB1) and its downstream target genes, such as cMyc, CyclinD1 (CCND1), and MMP2, was observed in human gastric cancer tissue samples." (PMID 36551233, 2022). "Interestingly, after miRNA‐206 inhibitor's transfection into gastric cancer cells, along with the recovery of the biological activity of SGC‐7901, CCND1 and CCND2 protein expression were enhanced simultaneously." (PMID 33473276, 2021). "Moreover, the analysis from database showed the positive correlation between expression of UBAP2L and that of wnt/β-catenin downstream target genes, CCND1, AXIN2, and MYC in gastric cancer tissues, suggesting that UBAP2L activated this signaling." (PMID 34823423, 2021). "Recent evidences suggested that activation of NLRP3 inflammasome by mycoplasma hyorhinis promotes gastric cancer migration and invasion, and this gastric tumor-promoting effect by NLRP3 may be due to the activating CCND1 transcription." (PMID 34211462, 2021). "In this research, HOTAIR silencing was effective in inhibiting the expression of CCND1 and CCND2 in gastric cancer cells, which might be related to HOTAIR silence's suppression of the biological activity of gastric cancer." (PMID 33473276, 2021). "In conclusion, HOTAIR’s positive regulation of CCND1 and CCND2 in gastric cancer may be realized by reverse regulation of miRNA‐206." (PMID 33473276, 2021). "The enrichment included the PI3K-Akt and IL-17 signaling pathways, and the network analysis showed that the Zhishi-Baizhu herb pair acted on seven key targets, namely, AKT1, MMP9, IL-6, CCND1, BCL2, MTOR, and MDM2 (where they played a role in treating gastric cancer)." (PMID 34899944, 2021). "Importantly, Kaplan-Meier survival analysis showed that gastric cancer patients with high AURKB and CCND1 expression levels had shorter overall survival than those with low AURKB and CCND1 expression levels." (PMID 31982864, 2020).
gastric cancer (continued). "To understand the mechanism underlying the cell cycle arrest of gastric cancer cells induced by knocking down AURKB, we next examined the effect of AURKB on various key cell cycle regulatory molecules, including CCND1, CDC16, CDC6, CDC26, CCNB2, CCNF, p27 and E2F1, in gastric cancer cells." (PMID 31982864, 2020). "Metastatic gastric cancer cell supernatant treatment significantly downregulated E-cadherin expression in peritoneal mesothelial cells, while it notably upregulated N-cadherin, α-SMA, Snail, Twist, Slug, Cyclin D1, MMP3 and MMP9 expression." (PMID 32139657, 2020). "The present results showed that ZYHT could decrease the expression of Bcl-2 and Cyclin D1, which may be the main mechanism of ZYHT promoting apoptosis and inhibiting proliferation on gastric cancer cells." (PMID 32382534, 2020). "Tumor suppressor miR-195-5p, miR-204, miR-623, miR-939 and miR-124 have been shown to be involved in overcoming 5-FU resistance of gastric cancer via silencing Zing finger 139 (ZNF139), TGFBR2, cyclin D1 (CCND1), solute carrier family 34 member 2 (SLC34A2) and EZH2, respectively." (PMID 32192494, 2020). "In gastric cancer, CCND1 has been shown to directly interact with TCF4 through the Wnt signaling pathway, suggesting that other mechanisms of CCND1 overexpression may also occur in MM." (PMID 31156714, 2019). "In the molecular level, DIM can arrest G1-phase cell cycle by reducing CDK4, and Cyclin D1 and elevating p21, a CDK (cyclin-dependent kinase) inhibitor.This finding is in line with previously reported mechanisms of DIM in gastric cancer and esophageal squamous carcinoma." (PMID 31396207, 2019). "Park found that 19-nor-1,25-dihydroxyvitamin D2, a vitamin D analog, could block cell cycle of MKN45 gastric cancer cells by decreasing the expression of cyclin-dependent kinase(CDK), CDK2, CDK4, CDK6 and Cyclin D1." (PMID 28206978, 2017). "Simvastatin, a cholesterol-lowering drug, can sensitize the gastric cancer to the antitumor effects of capecitabine through suppressing the constitutive activation of NF-κB and expression of COX-2, cyclin D1, Bcl-2, survivin, CXC motif receptor 4, and MMP-9 proteins in gastric cancer cells." (PMID 28350359, 2017). "Several gastric cancer cell lines showed the presence of constitutively-active STAT3, which functions to facilitate cell survival via upregulating the expression of its downstream target genes such as Survivin and Cyclin D1." (PMID 29383166, 2017). "Immunohistochemical analysis revealed that loss of the cell cycle regulators p21, p27, p16 and tumor suppressor APC, as well as increase of cyclin D1 and nuclear NF-κB accumulation were more often found in EBV-positive gastric carcinomas than in EBV-negative tumors." (PMID 28350359, 2017). "Strong correlation between higher expression levels of RelA, c-Myc, cyclin D1, Bcl-XL in intestinal but not diffuse types of gastric carcinoma was also found." (PMID 28350359, 2017). "Interestingly, in gastric cancer ASK1 promotes the expression of cyclin D1 via phosphorylation of JNK, and cyclin D1 increases ASK1 expression by activating the Rb/E2F pathway." (PMID 27655673, 2016). "The increased expression of APIP in gastric cancer cells enhances the HRG-β1/ERBB3-induced activation of AKT and ERK1/2 which stimulate cell proliferation and positively increase tumorigenesis by elevating ELK-1, C-FOS or cyclin D1." (PMID 26942872, 2016). "Gene amplifications of CCND1 and CDKN1B are potential candidates to serve as prognostic markers for the stratification of patients based on the estimate of survival in the management of gastric cancer patients." (PMID 27781065, 2016).
gastric cancer (continued). "YM155 significantly inhibited sphere formation of gastric cancer cells, suppressed expansion and growth of the formed spheres (cancer stem cell-like cells, CSCs) and downregulated the protein levels of β-catenin, c-Myc, Cyclin D1 and CD44 in gastric cancer cells." (PMID 26771139, 2016). "We found that DIM significantly inhibits gastric cancer cell growth in a dose-dependent manner with G1-phase cell cycle arrest by reducing the levels of the cyclin dependent kinase (CDK) 2, CDK4, CDK6, and Cyclin D1 proteins." (PMID 27447608, 2016). "Heterogeneity is common for the biomarkers HER2, CCND1, EGFR and MYC in gastric cancer and may therefore limit treatment decisions based on the analysis of a single clinical biopsy." (PMID 25649416, 2015). "Western blot, RT-PCR and real-time quantitative RT-PCR demonstrated that over-expression of miR-9 resulted in decreased protein and transcriptional levels of cyclin D1 and Ets1 in gastric cancer cells than those transfected with negative control vector (mock)." (PMID 23383271, 2013). "Upregulation of cyclin D1 has been described in gastric cancer; however, its prognostic value is not fully clear." (PMID 23420289, 2013). "Based on our results, it is possible that via the upregulation of Cyclin D1, EGFR, Bcl-2, MMP-9 and MMP-2 expression and MVD, CXCR1/2 and their ligands are involved in mediating proliferation, growth, angiogenesis, invasion and metastasis of gastric carcinoma." (PMID 23420470, 2013). "To primarily explore the downstream mechanism through which RhoC/IQGAP1 regulate the proliferation of gastric cancer cells, we investigated the effect of RhoC/IQGAP1 on the expression of cell cycle related proteins, including cyclin E, cyclin D1, cyclin B and cyclin dependent kinase (CDK)." (PMID 23145020, 2012). "In addition, a gastric cancer cell line SNU-668 was treated with a GSK-3β inhibitor lithium chloride (LiCl) to examine the correlation between GSK-3β and cyclin D1 expression." (PMID 20704706, 2010). "By exploring the correlation between lnc-CHAF1B-2 and key proteins in Wnt/β-catenin D1, which correspond to the genes CTNN GSK3B and CCND1, we hypothesized that lnc-CHAF1B-2 might promote the development and progression of gastric cancer through activation of the Wnt/β-catenin pathway." (PMID 39747989, 2025). "Moreover, its pathological role in tumorigenesis has been reported through the regulation of cyclin D1 and c-Myc genes in neuroblastoma, gastric cancer and non-Hodgkin lymphoma." (PMID 39737401, 2024). "Therefore, NCAPD3 knockdown may inhibit CCND1, MYC, and ESR1 expression to downregulate CDK6 and IRSI expression, thereby inhibiting the proliferation of gastric cancer cells." (PMID 38711992, 2024). "Therefore, NCAPD3 knockdown may inhibit CCND1, MYC, and ESR1 activity to downregulate CDK6 and IRS1 expression, thereby inhibiting the proliferation of gastric cancer cells." (PMID 38711992, 2024). "Therefore, NCAPD3 knockdown may inhibit CCND1 and ESR1 expression to downregulate CDK6 and IRSI expression, thereby inhibiting the proliferation of gastric cancer cells." (PMID 38711992, 2024). "The expression of cyclin D1 should not be detected in normal gastric mucosa, and there are significant trends (p < 0.01) for increased expression of cyclin D1 in non-neoplastic mucosa, including in conditions such as gastric atrophy, dysplasia, intestinal metaplasia, and gastritis to gastric cancer." (PMID 37687125, 2023). "MT2A expression was found to be decreased in gastric cancer cell lines and primary tumor tissues, and MT2A upregulation could significantly decrease cyclin D1 expression in gastric cancer cells, further indicating that MT2A upregulation could inhibit gastric cancer cell proliferation." (PMID 37091533, 2023).
gastric cancer (continued). "Here we show that in colorectal and gastric cancer patients, MG53 is downregulated in more than 80% of tumors compared to the normal gastrointestinal tissues from the same patient, and the reduced MG53 expression is correlated with increased cyclin D1 abundance and inferior survival." (PMID 37414783, 2023). "Likewise, in gastric cancer cells (SGC7901 and AGS lines), BBR treatment suppressed cell proliferation, induced cell cycle arrest, and attenuated invasion via the down-regulation of C-myc, cyclin-D1, and MMP-3 expressions, respectively." (PMID 34885950, 2021). "In gastric cancer (GC), SIRT1 silencing or inhibiting its activity by EX527 enhances expression of FOXO1, pro-apoptotic BAX, and E-cadherin, whereas the expression of Ki67, Cyclin D1, anti-apoptotic Bcl-2, Vimentin, MMP-2 and MMP-9 are downregulated, suggesting SIRT1 involvement in GC progression." (PMID 34769241, 2021). "To verify that CCND1 is a downstream target of AURKB, we investigated whether the restoration of CCND1 expression could reverse the AURKB knockdown-mediated inhibition of gastric cancer cell proliferation." (PMID 31982864, 2020). "For example, lncRNA ZFAS1 could enhance PTX resistance of SGC7901 gastric cancer cells by altering the expressions of EMT markers (E-cadherin, N-cadherin, and vimentin) and cell cycle related proteins (cyclin D1, cyclin E and cyclin B1), as well as the Wnt/β-catenin signaling." (PMID 32192494, 2020). "Therefore, cyclin D1 and vimentin might mediate the process of CORO1C increasing oncogenicity in human gastric cancer cells." (PMID 30974047, 2019). "Results showed that expression levels of NKX6.3, CDH1, CDKN1A, and EP300 were decreased while expression levels of NFκB p65, AICDA, CBFβ, APOBEC3A, APOBEC3B, RhoA, ROCK1, ROCK2, PIK3CA, and CCND1 were increased in CagA positive gastric cancers compared to those in CagA negative cases." (PMID 30514953, 2018). "Intra-tumor heterogeneity is a potential cause for failure of targeted therapy in gastric cancer, but the extent of heterogeneity of established (HER2) or potential (EGFR, CCND1) target genes and prognostic gene alterations (MYC) had not been systematically studied." (PMID 25649416, 2015). "Correlation analysis between CXCR1/2 and pAKT (P=0.032), pERK (P<0.001), Cyclin D1 (P=0.049), EGFR (P=0.013), Bcl-2 (P=0.003), microvessel density (P=0.001), MMP-9 (P=0.013) and MMP-2 (P=0.027) expression using the Spearman test showed significant correlation in gastric carcinoma." (PMID 23420470, 2013). "In gastric cancer (GC), circNFATC3 binds to IGF2BP3 to enhance the stability of IGF2BP3 by suppressing TRIM25‐mediated ubiquitination, enhancing the IGF2BP3‐CCND1 regulatory axis and elevating CCND1 mRNA stability to promote the proliferation of GC cells." (PMID 39901896, 2025). "Furthermore, in a gastric cancer (GC) model, NLRP3 promoted CyclinD1 gene (CCND1) transcription, enhancing GC proliferation and tumorigenesis." (PMID 35745570, 2022). "Indeed, the expression of CDK4, CDK6 and cyclin D1, which are expressed predominantly in the G1 phase and promotes the transition to S phase of the cell cycle, closely correlated with the expression of YES1 and YAP1 in gastric cancer cells and tumor xenografts." (PMID 35017464, 2022). "It is proposed that ERK/Cyclin D1 could act as specific effectors of VEGF signaling to elicit excessive angiogenesis behavior, and thus facilitated cell proliferation, suggesting a crucial role of the molecules in the initiation and progression of gastric cancer." (PMID 30200948, 2018). "Furthermore, treatment of gastric cancer cells with LiCl did not change cyclin D1 expression." (PMID 20704706, 2010). "Elevated level of NF-κB and its target, cyclin D1, was observed in BARF1-expressing gastric cancer cells compared with BARF1 non-expressing cells." (PMID 33072180, 2020).
gastric cancer (continued). "Thus, the negative correlation between Mist1 and Cyclin D1 expression might indicate the multiple roles of Mist1 in inhibiting EMT and gastric cancer cell proliferation via Wnt/β-catenin." (PMID 34149921, 2021). "Lastly, a CCND1/CDKN2A assay with clinical samples showed that uterine cervical and small cell lung cancers known to have a high prevalence of RB1-decifiency were predicted to be 100% RB1-negative, while uterine endometrial or gastric cancers were predicted to be 5-22% negative." (PMID 21447152, 2011). "DNA amplification was detected at chromosomal regions 17q21.1(harboring HER-2), 11q13.3 (CCND1), and 11q13 (FGF4) in four, three, and three tumors, respectively, though the amplification was not correlated with any clinicopathological feature of the gastric cancers." (PMID 19115996, 2008). "Western blot demonstrated that neither expression of Cyclin D1 nor Cyclin B1 were influenced by ectopic expression of RPL15, indicating there might be other molecules mediating the promoting effect of RPL15 on cell proliferation of gastric cancer." (PMID 16608517, 2006).